TIPE2 (TNF alpha induced protein 8 like 2)
Diseases named in the same sentence as TIPE2 in open-access papers (continued):
Sharing a sentence is not in itself a finding about the gene and the disease.
esophageal cancer (4 papers, 2019 to 2025). A primary or metastatic malignant neoplasm involving the esophagus. "TIPE2 also could inhibit esophageal cancer by blocking the Wnt/β-catenin pathway." (PMID 35388275, 2022).
lung adenocarcinoma (4 papers, 2015 to 2025). A carcinoma that arises from the lung and is characterized by the presence of malignant glandular epithelial cells. "We examined the expression of TIPE2 in lung squamous cancer (LSC), small cell lung cancer and lung adenocarcinoma (AdC) tissues and found that TIPE2 expression was lost in small cell lung cancer, compared with adjacent non-tumor tissues." (PMID 25946186, 2015). "The results showed that there was a direct positive relationship between TIPE2 and CD8 mRNA expression in human lung adenocarcinoma in the TCGA database, but the altered TIPE2 expression tumor group had lower overall survival probability than unaltered tumor group." (PMID 39851538, 2025). "However, the data were not available to determine the relationship between the expression of TIPE2 and CD8 in the MDSCs of the same lung adenocarcinoma set in the TCGA database." (PMID 39851538, 2025). "However, we analyzed the data for TIPE2 and CD8 mRNA expression in human lung adenocarcinoma in the TCGA database using the cBioPortal website tools." (PMID 39851538, 2025).
lymph node metastasis (4 papers, 2016 to 2022). "TIPE2 expression was negatively correlated with lymph node metastasis (p = 0.004) and disease progression (p = 0.021)." (PMID 35388275, 2022). "We also found that TIPE2 expression was negatively correlated to lymph node metastasis and disease progression of bladder cancer patients." (PMID 35388275, 2022). "We also found that TIPE2 expression was closely related to lymph node metastasis and the prognosis of PDAC patients." (PMID 33850476, 2021). "ROC analysis indicated that TIPE2 expression also had discriminative validity in distinguishing lymph node metastasis." (PMID 27556698, 2016). "TIPE2 upregulation in human NSCLC tissues was negatively associated with the primary tumor size, lymph node metastasis, and advanced clinical stage, which can be used to predict lymph node metastasis." (PMID 27556698, 2016). "In addition, the ROC curve showed that TIPE2 better distinguished lymph node metastasis." (PMID 33850476, 2021). "By IHC staining, we also found that the TIPE2 levels decreased in tumor tissues with lymph node metastasis (LNM) compared to those in tumor tissues without LNM (P<0.001)." (PMID 33850476, 2021). "TIPE2 expression was negatively correlated with TNM stage and lymph node metastasis." (PMID 33850476, 2021).
non-small cell lung carcinoma (4 papers, 2017 to 2021). A group of at least three distinct histological types of lung cancer, including non-small cell squamous cell carcinoma, adenocarcinoma, and large cell carcinoma. "Deficiency of TIPE2 expression has also been found in non-small cell lung cancer (NSCLC) and renal cell carcinoma, which is associated with tumor metastasis and TNM staging." (PMID 30157801, 2018). "Similarly, the expression of TIPE2 is also elevated in renal carcinoma, non-small cell lung cancer (NSCLC) and skin squamous cancer 41-44." (PMID 33850476, 2021).
rheumatoid arthritis (4 papers, 2017 to 2023). A chronic, systemic autoimmune disorder characterized by inflammation in the synovial membranes and articular surfaces. "TIPE2 regulates macrophage M2 polarization and the low expression of pro-inflammatory factors by activating signal transducer and activator of transcription 3 and NF-κB signaling pathways to treat rheumatoid arthritis." (PMID 36983674, 2023). "Thus, using this novel target, TIPE2, therapeutic strategies against rheumatoid arthritis can be designed and used for protection against this disease." (PMID 30274259, 2018). "Additionally, the expression of tumor necrosis induced protein 8-like 2 (TIPE2) and PCNP in peripheral blood mononuclear cells of active rheumatoid arthritis (RA) patient has abnormally increased, and there was a positive correlation between them." (PMID 36703786, 2022).
Sepsis (4 papers, 2015 to 2021). Sepsis is defined as life-threatening organ dysfunction caused by a dysregulated host response to infection. "Taken together, our results suggest that TIPE2 can exacerbate sepsis-induced DCs immune dysfunction by restricting autophagy via the TAK1-JNK pathway." (PMID 34718337, 2021). "This study aimed to determine the correlations among DCs TIPE2 expression, autophagic activity and immune function in the context of sepsis." (PMID 34718337, 2021). "In summary, to the best of our knowledge, this work is the first investigation to explore the relationship between TIPE2 and autophagy in DCs in sepsis." (PMID 34718337, 2021). "Several studies have shown that TIPE2 can inhibit NF-κB activation, thereby reducing the generation of proinflammatory mediators and attenuating the sepsis-induced inflammatory response." (PMID 31927655, 2020). "Our study demonstrated that DEX inhibits acute inflammation and apoptosis in a murine model of sepsis-stimulated ALI via the upregulation of TIPE2 and the suppression of the activation of the NF-κB and JNK signalling pathways." (PMID 31927655, 2020). "By observing changes in thymus T lymphocytes, TIPE2 and immune cells in mice with sepsis which were pre-treated with Rhodiola rosea extract, the present study aimed to elucidate the immune regulatory mechanisms of Rhodiola rosea." (PMID 26063084, 2015). "However, the more precise mechanism by which TIPE2 affects immune functions of DCs in sepsis is still needed to be elucidated, which is the main subject of our forthcoming study." (PMID 34718337, 2021). "Furthermore, our previous study showed that the expression of TIPE2 was negatively correlated with the immune function of DCs in the context of burn injury or sepsis." (PMID 34718337, 2021). "In addition, TIPE2 knockout (KO) in DCs significantly enhanced autophagy and improved the immune response of DCs in sepsis." (PMID 34718337, 2021). "The aim of the present study was to investigate whether TIPE2 participates in the protective actions of dexmedetomidine (DEX) in a mouse model of sepsis-induced acute lung injury (ALI)." (PMID 31927655, 2020). "In addition, in a sepsis-induced mouse model treated with low doses of endotoxin, septic shock occurred in TIPE2-knockout mice." (PMID 26063084, 2015). "Furthermore, TIPE2-deficient cells were found to be highly responsive to the activation of TLR and T-cell receptor signals; in addition, in the low-dose LPS-induced sepsis model, TIPE2-knockout mice demonstrated clear septic shock responses compared with those of normal WT mice." (PMID 25405912, 2015).
small cell lung carcinoma (4 papers, 2015 to 2021). Small cell lung cancer (SCLC) is a highly aggressive malignant neoplasm, accounting for 10-15% of lung cancer cases, characterized byrapid growth, and early metastasis. "We found that TIPE2 expression was down-regulated in lung squamous carcinoma and even almost lost in small cell lung cancer." (PMID 25946186, 2015). "The findings showed that TIPE2 expression was lost in small cell lung cancer in comparison with the nearby non-malignant tissues." (PMID 31817720, 2019).
Arthritis (3 papers, 2019 to 2023). Inflammation of a joint. "In addition, the overexpression of TIPE2 in macrophages can play a negativerole in innate immunity by inhibiting TLR signal transduction in arthritis." (PMID 31778525, 2019).
autoimmune disorders (3 papers, 2017 to 2021). "In summary, our study has revealed that TIPE2 can function as both a negative and positive regulator of autoimmunity." (PMID 31616442, 2019).
Cirrhosis (3 papers, 2013 to 2019). A chronic disorder of the liver in which liver tissue becomes scarred and is partially replaced by regenerative nodules and fibrotic tissue resulting in loss of liver function. "Second, other HBV associated liver diseases including cirrhosis, acute hepatitis, and liver failure should be included to explore the comprehensive role of TIPE2 in the whole progression of HBV infection." (PMID 28390195, 2017). "In fact, our present study is a type of cross-sectional study with the results showing that TIPE2 expression is higher in CHB and CHB with cirrhosis but lower in CHB with HCC." (PMID 31661000, 2019).
colitis (3 papers, 2018 to 2026). Inflammation of the colon. "In the current study, we investigated the roles of Tipe2 in senescence using a colitis-associated CRC model and D-Gal-induced aging model." (PMID 34702807, 2021). "Consistent with Lou’s report that Tipe2-deficiency suppressed the DSS-associated colitis in mouse model, we reported that AOM/DSS-treated Tipe2 KO mice exhibited significantly less severe colitis and this might result in less severe tumorigenesis." (PMID 34702807, 2021). "In addition, it was observed that TIPE2-deficient mice with ameliorated DSS-induced colitis also displayed a weaker systemic inflammatory response together with reduced local dissemination of commensal bacteria." (PMID 30274259, 2018). "To investigate the role of Tipe2 in colitis-associated CRC, we used a protocol that combines the AOM carcinogen with DSS-induced colitis." (PMID 34702807, 2021). "Altogether, these two findings indicate that both TIPE and TIPE2 play important roles in the maintenance of colon homeostasis and the prevention and treatment of colitis." (PMID 30274259, 2018). "Further, it was observed that the degree of severity of colitis, as well as colonic damage in TIPE2-deficient mice, was notably less and was plausibly attributed to the decreased colonic expression of inflammatory cytokines TNF-α, interleukin (IL)-6, and IL-12." (PMID 30274259, 2018). "TIPE2 plays a vital role in inflammatory cell function and commensal bacteria dissemination regulation in dextran sodium sulfate (DSS)-induced colitis." (PMID 30274259, 2018).
diabetes (3 papers, 2017 to 2018). "To further investigate the role of TIPE2 in diabetes, we studied the relationship between TIPE2 mRNA expression and the serum concentrations of hsCRP, TNF-α, and IL-6." (PMID 28626770, 2017). "Although TIPE2 plays a key role in inflammatory homeostasis, its exact role in type 2 diabetes mellitus (T2DM) remains unknown." (PMID 30274259, 2018). "The role of TIPE2 in type 2 diabetes mellitus (T2DM) remains unknown, although TIPE2 plays key roles in preserving inflammatory homeostasis." (PMID 28626770, 2017).
rectal adenocarcinoma (3 papers, 2019 to 2022). "To investigate the clinical significance of TIPE2 in human rectal adenocarcinoma, we further analysed the association of TIPE2 expression to clinicopathological parameters in rectal adenocarcinoma tissue chip." (PMID 30637920, 2019). "Interestingly, TIPE2 expression was found to be associated with disease grade of rectal adenocarcinoma." (PMID 30637920, 2019). "In addition, TIPE2 expression was found to be associated with disease grade of rectal adenocarcinoma." (PMID 30637920, 2019). "In conclusion, TIPE2 can regulate the apoptosis, proliferation, migration and invasion of human rectal adenocarcinoma cells through the Wnt/β-Catenin signaling pathway." (PMID 35836256, 2022). "TIPE2 overexpression increases apoptosis by down-regulating the expression levels of Wnt3a, phospho(p)-β-Catenin and p-glycogen synthase kinase-3β in rectal adenocarcinoma cells." (PMID 35836256, 2022). "To explore the expression of TIPE2 protein in human rectal adenocarcinoma tissues, we detected TIPE2 expression in human rectal adenocarcinoma tissue chip that consists of 86 rectal adenocarcinoma specimens and corresponding adjacent tissues by IHC." (PMID 30637920, 2019). "We further examined the effects of TIPE2 on tumour growth and angiogenesis in nude mice xenografted with human rectal adenocarcinoma." (PMID 30637920, 2019). "We then investigated the mechanism of action of TIPE2 on the proliferation, migration, and invasion of human rectal adenocarcinoma cells." (PMID 30637920, 2019). "Our results showed that the expression levels of TIPE2 in human rectal adenocarcinoma tissues were higher than those in adjacent non‐tumour tissues." (PMID 30637920, 2019). "The results showed that comparing to adjacent tissues, TIPE2 protein was highly expressed in all clinical stages of human rectal adenocarcinoma." (PMID 30637920, 2019). "Taken together, these results show that TIPE2 plays an important role in regulating the migration and invasion of human rectal adenocarcinoma cells." (PMID 30637920, 2019). "In the present study, we initially examined the expression levels of TIPE2 in human rectal adenocarcinoma specimens." (PMID 30637920, 2019). "TIPE2 overexpression notably reduced the growth of rectal adenocarcinoma xenograft tumours, whereas TIPE2 knockdown markedly promoted tumour growth." (PMID 30637920, 2019). "Overexpression of TIPE2 reduced the proliferation, migration, and invasion of human rectal adenocarcinoma cells and down‐regulation of TIPE2 showed reverse effects." (PMID 30637920, 2019). "TIPE2 overexpression decreased autophagy by reducing the expression levels of p‐Smad2, p‐Smad3, and transforming growth factor‐beta (TGF‐β) in rectal adenocarcinoma cells, however, TIPE2 knockdown showed opposite effects." (PMID 30637920, 2019). "TIPE2 overexpression increased apoptosis through down‐regulating the expression levels of Wnt3a, phospho (p)‐β‐Catenin, and p‐glycogen synthase kinase‐3β in rectal adenocarcinoma cells, however, TIPE2 knockdown exhibited reverse trends." (PMID 30637920, 2019). "In addition, TIPE2 overexpression reduced the growth of xenograft human rectal adenocarcinoma, while TIPE2 knockdown promoted the growth of rectal adenocarcinoma tumors by regulating angiogenesis." (PMID 35836256, 2022). "In sum, these results show that TIPE2 could mediate the growth and angiogenesis of human rectal adenocarcinoma xenograft tumours." (PMID 30637920, 2019). "All these results reveal that TIPE2 could mediate the proliferation and viability of human rectal adenocarcinoma cells." (PMID 30637920, 2019). "TIPE2 showed similar effect on the viability of human rectal adenocarcinoma cells." (PMID 30637920, 2019). "Therefore, we can conclude that TIPE2 modulates apoptosis through the Wnt/β‐Catenin signalling pathway in human rectal adenocarcinoma cells." (PMID 30637920, 2019). "TIPE2 is a potential therapeutic target for the treatment of rectal adenocarcinoma." (PMID 30637920, 2019).
rectal adenocarcinoma (continued). "Considering its role in the developmental process of human rectal adenocarcinoma cells, TIPE2 could be a potential therapeutic target for advanced and recurrent human rectal adenocarcinoma." (PMID 30637920, 2019). "All these data suggest that TIPE2 could serve as a promising biomarker for the diagnosis and prognosis of rectal adenocarcinoma and may act as a growth regulator in human rectal adenocarcinoma cells." (PMID 30637920, 2019). "Furthermore, TIPE2 overexpression reduced the growth of xenografted human rectal adenocarcinoma, whereas TIPE2 knockdown promoted the growth of rectal adenocarcinoma tumours by modulating angiogenesis." (PMID 30637920, 2019). "In conclusion, TIPE2 could regulate the proliferation, migration, and invasion of human rectal adenocarcinoma cells through Wnt/β‐Catenin and TGF‐β/Smad2/3 signalling pathways." (PMID 30637920, 2019). "Collectively, the results indicate that TIPE2 could modulate autophagy through the TGF‐β/Smad2/3 signalling pathway in human rectal adenocarcinoma cells." (PMID 30637920, 2019). "Furthermore, the present study indicates that TIPE2 could mediate the proliferation, migration, and invasion of human rectal adenocarcinoma cells through Wnt/β‐Catenin and TGF‐β/Smad2/3 signalling pathways." (PMID 30637920, 2019). "However, the mechanism of action of TIPE2 on the growth of rectal adenocarcinoma is unknown." (PMID 30637920, 2019). "In conclusion, our results demonstrate that TIPE2 can be detected in human rectal adenocarcinoma cells and the expression levels of TIPE2 in human rectal adenocarcinoma tissues are higher than those in adjacent nontumour tissues." (PMID 30637920, 2019).
renal carcinoma (3 papers, 2013 to 2021). A carcinoma arising from the epithelium of the renal parenchyma or the renal pelvis. "However, TIPE2 was over expressed in kidney renal cancer tissues compared with normal kidney tissues and its expression level was positively correlated with TNM staging." (PMID 33817189, 2019). "Therefore, the upregulation of TIPE2 expression in renal cancer tissue from patients with RCC may be wholly or partially responsible for the reduced levels of inflammatory cytokines." (PMID 24137373, 2013). "The mRNA expression levels of TIPE2 and myxoma resistance protein 1 (MX1; a type I interferon-inducible gene) were investigated in renal cancer tissues." (PMID 24137373, 2013).
viral infections (3 papers, 2016 to 2021). "At the protein expression level, the variation of TIPE2 is a similar dynamic trend, which together represents that TIPE2 is also anomalous and likely performing certain functions in RNA viral infectious diseases." (PMID 33815396, 2021). "Consistently, overexpression of TIPE2 inhibited the production of type I IFNs and pro-inflammatory cytokines, and thus promoted the viral infection." (PMID 33815396, 2021). "Type I IFNs induced by viral infection have extremely vital significance in antiviral innate immunity, for further validation, feasibility assessment regarding the inhibition of TIPE2 against virus-induced type I IFN response was implemented in vitro." (PMID 33815396, 2021). "So we predict that the upregulation of γ-H2AX, pChk1, and pChk2 in TIPE2 deficiency cells and HCC tumor tissue indicates that TIPE2 inhibits DDR during virus infection likely via the Rac pathway." (PMID 27696294, 2016). "Accumulating evidences indicated that TIPE2 might limit T cell responses during chronic viral infections." (PMID 28390195, 2017). "The data above further confirmed that TIPE2 negatively regulates type I IFN response and promotes viral infection in macrophages." (PMID 33815396, 2021).
autoimmune hepatitis (2 papers, 2018). Hepatitis caused by autoantibodies. "Another study investigated the expression of TIPE2 in mice PBMCs with autoimmune hepatitis (AIH) and its involvement in the pathogenesis of AIH." (PMID 30274259, 2018).
bladder cancer (2 papers, 2022 to 2025). "Their results uncovered the different degrees of TIPE2 expression in bladder cancer tissues, with both cytoplasmic and nuclear location." (PMID 40060230, 2025). "It was detected that TIPE2 expression was related to low stages of UC and negatively correlated to distant metastasis and relapsing illness in bladder cancer patients." (PMID 40060230, 2025). "The present study analyzed the expression and significance of TIPE2 in bladder cancer tissues by retrospective data and IHC staining." (PMID 35388275, 2022). "Taken together, these data demonstrate that TIPE2 expression may serve as a biomarker for unfavorable outcome in patients with bladder cancer." (PMID 35388275, 2022). "Immunohistochemical (IHC) staining of TIPE2 in 110 cases of bladder cancer after postoperative pathological paraffinized tissue sections showed that TIPE2 was stained in different degrees in bladder cancer tissues and expressed in both the nucleus and the cytoplasm." (PMID 35388275, 2022). "Finally, we need to assess the prognostic value of cytoplasmic versus nuclear TIPE2 expression in bladder cancer." (PMID 35388275, 2022). "Therefore, we hypothesized that TIPE2 may play an important role in the development and progression of bladder cancer." (PMID 35388275, 2022). "This study aimed to identify TIPE2 and CD36 expressions in cancer bladder and examine their relationship with clinicopathological data and prognosis." (PMID 40060230, 2025).